RPS6KA5 (ribosomal protein S6 kinase A5)
Description:
Serine/threonine-protein kinase that is required for the mitogen or stress-induced phosphorylation of the transcription factors CREB1 and ATF1 and for the regulation of the transcription factors RELA, STAT3 and ETV1/ER81, and that contributes to gene activation by histone phosphorylation and functions in the regulation of inflammatory genes. Phosphorylates CREB1 and ATF1 in response to mitogenic or stress stimuli such as UV-C irradiation, epidermal growth factor (EGF) and anisomycin. Plays an essential role in the control of RELA transcriptional activity in response to TNF and upon glucocorticoid, associates in the cytoplasm with the glucocorticoid receptor NR3C1 and contributes to RELA inhibition and repression of inflammatory gene expression. In skeletal myoblasts is required for phosphorylation of RELA at 'Ser-276' during oxidative stress. In erythropoietin-stimulated cells, is necessary for the 'Ser-727' phosphorylation of STAT3 and regulation of its transcriptional potential. Phosphorylates ETV1/ER81 at 'Ser-191' and 'Ser-216', and thereby regulates its ability to stimulate transcription, which may be important during development and breast tumor formation. Directly represses transcription via phosphorylation of 'Ser-1' of histone H2A. Phosphorylates 'Ser-10' of histone H3 in response to mitogenics, stress stimuli and EGF, which results in the transcriptional activation of several immediate early genes, including proto-oncogenes c-fos/FOS and c-jun/JUN. May also phosphorylate 'Ser-28' of histone H3. Mediates the mitogen- and stress-induced phosphorylation of high mobility group protein 1 (HMGN1/HMG14). In lipopolysaccharide-stimulated primary macrophages, acts downstream of the Toll-like receptor TLR4 to limit the production of pro-inflammatory cytokines (By similarity). Functions probably by inducing transcription of the MAP kinase phosphatase DUSP1 and the anti-inflammatory cytokine interleukin 10 (IL10), via CREB1 and ATF1 transcription factors (By similarity). Plays a role in neuronal cell death by mediating the downstream effects of excitotoxic injury (By similarity). Phosphorylates TRIM7 at 'Ser-107' in response to growth factor signaling via the MEK/ERK pathway, thereby stimulating its ubiquitin ligase activity.
Synonyms: MSK1; RLPK; MSPK1
Tractability: Small molecule: a structure with a bound ligand is known; a high-quality ligand is known; it has a high-quality binding pocket; it belongs to a druggable protein family. PROTAC: UniProt records ubiquitination sites on it; ubiquitination databases record sites on it; its protein half-life has been measured; a small molecule that binds it is known.
Target class: AGC protein kinase group; AGC protein kinase RSK family; Kinase; AGC protein kinase MSK subfamily; Protein Kinase; Enzyme
Gene: Protein-coding gene on chromosome 14 (90,847,861 to 91,060,682, reverse strand). Ensembl gene ENSG00000100784.
Subcellular location: Nucleus; Cytoplasm
Subcellular location (Human Protein Atlas): Nucleoplasm
Pathways (Reactome):
Developmental Biology: NCAM signaling for neurite out-growth; Recycling pathway of L1
Signal Transduction: CREB phosphorylation; ERK/MAPK targets
Immune System: CD209 (DC-SIGN) signaling
Gene Ontology:
Molecular function: ATP binding; histone H2AS1 kinase activity; histone H3S10 kinase activity; histone H3S28 kinase activity; protein binding; protein serine kinase activity; protein serine/threonine kinase activity; protein tyrosine kinase activity; magnesium ion binding; protein kinase activity
Biological process: interleukin-1-mediated signaling pathway; intracellular signal transduction; negative regulation of DNA-templated transcription; positive regulation of transcription by RNA polymerase II; post-translational protein modification; protein phosphorylation; regulation of DNA-templated transcription; axon guidance; negative regulation of cytokine production; TORC1 signaling; chromatin remodeling; regulation of postsynapse organization
Cellular component: cytoplasm; nucleoplasm; nucleus
Genetic constraint (gnomAD): Loss-of-function variants: 19 observed, 57.42 expected, observed/expected ratio (o/e) 0.33, 90% interval 0.23 to 0.49. The upper end of that interval is the gene's LOEUF score, 0.49, which puts it in group 2 of 6, group 1 being the genes least tolerant of losing a copy. Missense variants: 627 observed, 764.34 expected, observed/expected ratio (o/e) 0.82, 90% interval 0.77 to 0.88. Synonymous variants: 263 observed, 279.43 expected, observed/expected ratio (o/e) 0.94, 90% interval 0.85 to 1.04.
Homologues: Orthologues: chimpanzee RPS6KA5 (100% identical), macaque RPS6KA5 (99% identical), pig RPS6KA5 (97% identical), dog RPS6KA5 (96% identical), mouse Rps6ka5 (96% identical), rat Rps6ka5 (96% identical), rabbit RPS6KA5 (96% identical), guinea pig RPS6KA5 (96% identical), zebrafish rps6ka5 (76% identical), Caenorhabditis elegans rskn-2 (46% identical), Drosophila melanogaster JIL-1 (43% identical), Drosophila melanogaster S6k (25% identical), and 3 more. Paralogues in human: RPS6KA4 (62% identical), RPS6KA6 (41% identical), RPS6KA3 (40% identical), RPS6KA2 (39% identical), RPS6KA1 (39% identical), RPS6KB1 (26% identical), RPS6KB2 (25% identical).
Diseases named in the same sentence as RPS6KA5 in open-access papers:
RPS6KA5 is named in the same sentence as 81 diseases in open-access papers, as found by Europe PMC text mining. Sharing a sentence is not in itself a finding about the gene and the disease. The quoted sentences say what the papers report.
breast carcinoma (20 papers, 2013 to 2025). "Under stress conditions, this luminal differentiation program is collectively regulated by kinase MSK1 (mitogen- and stress-activated kinase 1, encoded by RPS6KA5 gene), thereby facilitating dormancy in breast cancer cells." (PMID 34685621, 2021).
lung carcinoma (4 papers, 2012 to 2024). "It has been reported that RPS6KA5 can act as a tumor-associated antigen (TAAs) in lung cancer to distinguish lung cancer patients from healthy people." (PMID 36713456, 2022). "RPS6KA5 has been implicated to be involved in immune response of lung cancer." (PMID 38012744, 2023). "The bioinformatics analysis identified five favorable prognostic MTGs (RPS6KA5, RORA, SH3BP5, NUPR1, and CD40LG) for NSCLC patients, all of which was downregulated in lung cancer tissues as compared with normal tissues." (PMID 39135791, 2024). "As result, we identified five target genes of metformin (RPS6KA5, RORA, SH3BP5, NUPR1, and CD40LG), which were significantly correlated with favorable prognosis and immune infiltration in lung cancer patients." (PMID 39135791, 2024). "RPS6KA5, as a substrate of MAPK activated protein kinase family, was found to induce humoral immune response and its autoantibody could be used to diagnosis lung cancer." (PMID 39135791, 2024).
bladder cancer (2 papers, 2022 to 2023). "The KEGG bladder cancer pathway activation in poor prognosis CRCs was mostly due to increased expression of functional nodes HRAS/KRAS/NRAS, ARAF/BRAF/RAF1, MAPK1/MAPK3, and RPS6KA5." (PMID 36316649, 2022).
colon cancer (2 papers, 2019 to 2021). "The RPS6KA5 gene encodes for a tyrosine kinase and has been indicated as a biomarker for colon cancer through interaction with hsa-miR-130a." (PMID 34178670, 2021). "Among the upstream regulators (TFs, kinases, and MMTRs) of the DEGs, the expression of STAT3, RPS6KA5, IKBKE, ERBB2, MTOR, and NFKB1 had a positive correlation with OS in colon cancer, while the expression of CDK1, CDK5, and BRD2 had a negative correlation with OS in colon cancer." (PMID 31186640, 2019).
colorectal cancer (2 papers, 2020 to 2025). A primary or metastatic malignant neoplasm that affects the colon or rectum. "According to the previous literature, one of the causes of sporadic colorectal cancers is RPS6KA5 frameshift mutation, which leads to the same consequence as being targeted by miRNAs." (PMID 32964043, 2020).
depression (2 papers, 2022 to 2025). "The RPS6KA5 locus on 14q32.11-q32.12 was associated with depression." (PMID 40949012, 2025).
embryonal carcinoma (2 papers, 2013 to 2022). A non-seminomatous malignant germ cell tumor characterized by the presence of large germ cells with abundant cytoplasm resembling epithelial cells, geographic necrosis, high mitotic activity, and pseudoglandular and pseudopapillary structures formation. "Among expression-related genes, CDX4 and FOXD3 were significantly overexpressed in embryonal carcinoma, whereas CUX2 and RPS6KA5 were increased in seminoma." (PMID 36713456, 2022).
viral infection (2 papers, 2020 to 2024). "RPS6KA5 (ENSG00000100784), as the second parameter gene, has been shown to be down regulated during SARS-CoV-2 pathogenesis comparing to other virus infection." (PMID 33505977, 2020).
Hyperglycemia (1 paper, 2023). An increased concentration of glucose in the blood. "BeWo cytotrophoblasts exposed to hyperglycemia displayed increased mRNA expression of ACSL1, HSD11B2, RPS6KA5, and LAP3 and reduced mRNA expression of CYP2F1, and HK2, concomitant with increased levels of: lactate, malonate, and riboflavin metabolites." (PMID 36930661, 2023).
manic episodes (1 paper, 2024). "Moreover, the Circadian entrainment caused by RPS6KA5 has been proven to be connected with manic episodes." (PMID 38505796, 2024).
seminoma (1 paper, 2022). A radiosensitive malignant germ cell tumor found in the testis (especially undescended), and extragonadal sites (anterior mediastinum and pineal gland). "We found that CUX2 and RPS6KA5 were significantly overexpressed in the TGCT cohort of seminoma, and the same results were obtained by quantitative PCR." (PMID 36713456, 2022).
cancer (25 papers, 2011 to 2025). A tumor composed of atypical neoplastic, often pleomorphic cells that invade other tissues. "Metascape database analysis revealed that the target mRNAs PRKACB and PDCD4 of miR-550a-3p as well as RPS6KA5 and BCL2L2 of miR-550a-5p were associated with miRNA cancer pathway, providing important clues for subsequent studies on the mechanism underlying EAC development." (PMID 36829221, 2023). "Another very prominent pathway in cancer is ERK/MAPK signaling (p = 3.47 × 10−2; ESR1, FYN, ITGA3, PIK3R3, PLA2G4A, PLA2G5, RPS6KA5), which is the core of the signaling network involved in regulating cell growth, development, and division and a target of many cancer therapeutics." (PMID 35106465, 2022). "In the cancer pathway, five genes (WNT1, DLL, TRAF1, GST, and GADD45) were upregulated, while CASP3, IKBKA, STAT5A, RPS6KA5, BIRC5, BIRC2/3, and SKP2 were downregulated." (PMID 40723320, 2025). "A total of 20 target mRNAs of three miRNAs were predicted, among which seven target mRNAs—ASAP3, BCL2L2, LMF1, PPM1L, PTPN21, SLC18A2, and NR3C2—had prognostic value; PRKACB, PDCD4, RPS6KA5, and BCL2L2 were enriched in the miRNA cancer pathway." (PMID 36829221, 2023).
tumor (24 papers, 2013 to 2025). "It has been demonstrated that RPS6KA5 is downregulated in tumor tissues of PTC." (PMID 34335744, 2021). "The CIS RPS6KA5 was deleted in approximately 25% of GBMs and was also found in the top 7% of genes down-regulated at the mRNA level in the microarray dataset, implicating it as a candidate tumor suppressor gene." (PMID 25423036, 2014). "The results show that repression of m3Es proximal to CBX8 (m3eCBX8) and RPS6KA5 (m3eRPS6KA5) caused significant inhibition of tumor volume and weight; and repression of m3eTNFSF10 caused significant reduction of tumor weight but not tumor volume." (PMID 38012744, 2023). "Gene enrichment analysis revealed that RELN and RPS6KA5 are associated with activation of cyclic AMP (cAMP) response element-binding protein (CREB) transcription factor (adjusted p-value<0.01), which is responsible for tumor initiation, progression, and metastasis." (PMID 32324757, 2020). "We found that MAP2K6, MAP3K5, MAP3K9, MAP3K12, RPS6KA2, RPS6KA5, and STAT1 were lowly expressed in tumor tissues; However, NFKB1, RAC1, SHC1, and TRAF2 are highly expressed compared to normal tissues." (PMID 36969076, 2023). "Then we injected the stable cell lines containing m3E sgRNAs for CBX8, CCND1, PTP4A3, RPS6KA5 and TNFSF10 into nude mice and checked whether tumor growth was repressed." (PMID 38012744, 2023).
RPS6KA5 also shares sentences with these, for which no sentence is quoted: asthma (5 papers); gastric cancer (5); infection (5); allergic contact dermatitis (3); prostate carcinoma (3); Sepsis (3); Anxiety (2); breast tumor (2); Cognitive impairment (2); Dyskinesia (2); Huntington disease (2); leiomyoma (2); melanoma (2); myocardial infarction (2); nasopharyngeal carcinoma (2); psoriasis (2); spinocerebellar ataxia type 1 (2); allergic asthma (1); Alzheimer disease (1); anemia (1); arrhythmogenic right ventricular cardiomyopathy (1); atherosclerosis (1); autism (1); autism spectrum disorder (1); cardiac hypertrophy (1); Cerebral ischemia (1); cocaine abuse (1); Coffin-Lowry syndrome (1); colorectal tumor (1); dilated cardiomyopathy (1).
A further 38 diseases each share a sentence with RPS6KA5 in 1 paper.